CXCL1 (C-X-C motif chemokine ligand 1)
Diseases named in the same sentence as CXCL1 in open-access papers (continued):
Sharing a sentence is not in itself a finding about the gene and the disease.
food allergy (2 papers, 2022 to 2025). Gastrointestinal disturbances, skin eruptions, or shock due to allergic reactions to allergens in food. "Within these, 113 genes (27.8%) have been previously associated with food allergy; within the top 10 DE genes, 8 genes have been previously linked to food allergy—C3, CXCL8, RARRES1, CXCL6, MUC5AC, CXCL1, and SAA3." (PMID 36452260, 2022).
fungal keratitis (2 papers, 2015 to 2023). "Our experiment confirmed that Dectin-1 in early period of innate immune in rat fungal keratitis can work through IL-1β, IL-6, CCL2, CXCL1, CXCL2 to recruit neutrophils and macrophages to participate anti-fungal immunity." (PMID 26427623, 2015). "Dectin-1 in early period of innate immune responses in rat fungal keratitis might work through IL-1β, IL-6, CCL2, CXCL1, CXCL2 to recruit neutrophils and macrophages to participate anti-fungal immunity." (PMID 26427623, 2015).
gonorrhea (2 papers, 2012 to 2018). A common sexually transmitted bacterial infection caused by Neisseria gonorrhoeae. "In Neisseria gonorrhoeae infections, there were higher protein levels of IL-6, CXCL1 and CXCL2 in the vaginal secretions of BALB/c mice." (PMID 22848503, 2012).
helminth infection (2 papers, 2020 to 2021). "In this study, eosinophil numbers in the skin after allergen challenge were not affected by helminth infection, however, their production of the neutrophil chemoattractants CXCL1 and CXCL2 were, and this resulted in a greatly reduced neutrophil influx." (PMID 32508831, 2020).
Hyperinsulinemia (2 papers, 2017 to 2023). An increased concentration of insulin in the blood. "HbA1c correlated positively with changes of MCP-2 and IL-15-RA during hyperinsulinemia (Rho ≥ 0.51) and inversely with changes of CXCL1, MMP-1 and Axin-1 during hypoglycemia (Rho ≤ -0.55)." (PMID 37400734, 2023).
Hyperkeratosis (2 papers, 2017 to 2023). Hyperkeratosis is a histopathological term defining a thickened stratum corneum and may be present in many different skin conditions, with many possible overlaps. "We observed a significant increase in inflammatory factors (such as TNF-α, IL-1β, CXCL1, CXCL2, CCL4, and TLR7) and exacerbates hyperkeratosis and keratosis in STAT3 mice." (PMID 37465147, 2023).
hypertensive retinopathy (2 papers, 2022). Retinopathy due to hypertension. "We evaluated the expression levels of a series of chemokines (CXCL1, CXCL2, CXCL3 and CXCL5) and their receptor CXCR2 in Ang II-treated retinas to investigate the role of chemokines and their receptors in hypertensive retinopathy." (PMID 35981418, 2022).
idiopathic interstitial pneumonia (2 papers, 2016 to 2022). A class of diffuse lung diseases that typically affect the pulmonary interstitium, although some also have a component affecting the airways (for instance, Cryptogenic organizing pneumonitis). "It has also been shown that in autoimmune interstitial pneumonia and idiopathic interstitial pneumonia, elevated plasma levels of CXCL1 are clinically associated with DLco, erythrocyte sedimentation rate, and lung parenchymal extension." (PMID 35629314, 2022).
ileitis (2 papers, 2015 to 2024). "In addition, SHIP-1−/− mice exhibited increases in serum IL-12(p40) and CXCL1, and a reduction in IL-12(p70) and CCL5 that were independent of ileitis development." (PMID 39432107, 2024).
infarction (2 papers, 2015 to 2019). A localised pathological necrosis of tissue resulting from obstruction of the blood supply usually by a thrombus, an embolus, or vascular torsion. "Previously, CXCL1 has been associated with radiologically confirmed infarction after acute ischemic stroke and MS." (PMID 25970596, 2015). "Finally, based on our data, KC (CXCL1) and RANTES (CCL5) might also be considered important regulators of the immune response following prolonged myocardial I/R, as KC is significantly elevated in the serum and infarcted heart, peaking on day 1 after infarction." (PMID 30858476, 2019).
Klebsiella pneumonia (2 papers, 2014 to 2015). An pneumonia caused by infection with Klebsiella. "Jeyaseelan and colleagues reported that CXCL1 regulates expression of CXCL2 and CXCL5 during murine Klebsiella pneumoniae pneumonia." (PMID 25621893, 2015).
leptospirosis (2 papers, 2024). A contagious bacterial infection caused by spirochetes of the genus Leptospira. "Aligned with our findings, narrative reviews discussed the renal dysfunction associated with leptospirosis that resulted in secretion/expression of Fibronectin, iNOS, CCL2/MCP-1, TNFα, NFκB, CCL2/MIP2, CXCL1/KC through TLR2." (PMID 39729468, 2024). "It has been described that CXCL5 leads to CXCL3, CXCL1, and CXCL14 expression, which are all potent chemoattractants for neutrophils, indicating the occurrence of this mechanism on leptospirosis immune response." (PMID 39534703, 2024). "Notably, we observed the secretion/mRNA expression of several cytokines (IL6, IL8, IL-1β, TNFα, IFNγ, IL10, CCL2/MCP-1, CCL10, COX2, CXCL1/KC, CXCL2/MIP2) and immune effectors (hBD2, iNOS, Fibronectin, Oxygen, and Nitrogen reactive species) as key aspects of host TLR2 responses during leptospirosis." (PMID 39729468, 2024).
leukocytosis (2 papers, 2022 to 2023). "The rAcH3.3 instillation also increased apoptotic activity (cleavage of caspase 3 and 9) and triggered acute systemic inflammatory marker activation (TNF-α, IL-6, MCP-3, or CXCL-1) in plasma, accompanied by leukocytosis and lymphocytosis." (PMID 37759735, 2023).
Lyme borreliosis (2 papers, 2013 to 2017). "IL-17A, CXCL1 and CCL20 have however been reported present in other Lyme borreliosis manifestations, such as Lyme arthritis (IL-17), erythema migrans and acrodermatitis chronica atrophicans (CXCL1 and CCL20)." (PMID 28148307, 2017). "Thus, the B. burgdorferi-induced elaboration of IL-8 and CXCL-1 by astrocytes and HBMEC probably contribute to the neural damage associated with neuroborreliosis through recruitment of neurotoxic neutrophils." (PMID 23883071, 2013).
lymphopenia (2 papers, 2019 to 2021). Reduction in the number of lymphocytes. "Interestingly, the elevated IL-10 in the serum was correlated with the appearance of lymphopenia during FMDV infection but not IL-6, IL-2, IL-17, IL-18, IL-1β, TNF-α, IFN-α/β, TGF-β, and CXCL1." (PMID 34960627, 2021).
meningococcal infection (2 papers, 2025). Infections with bacteria of the species neisseria meningitidis. "The chemokine CXCL1/KC acts by recruiting and activating neutrophils as a host immune response to infection, and has been linked to meningococcal infection in this mouse model." (PMID 40818988, 2025). "Despite strain and donor variability, meningococcal infection universally induced cytokines CCL20, CXCL1, CXCL8, CXCL10, and IL-18, with significantly higher CCL20 levels 24 h post-MenW cc11 infection." (PMID 40586572, 2025). "Upon meningococcal infection, we observed a mostly universal induction of CCL20, CXCL1, CXCL8, CXCL10, and IL-18 secretion 24 h post-infection, regardless of the specific meningococcal strain used for infection." (PMID 40586572, 2025).
mesothelioma (2 papers, 2024). A usually malignant and aggressive neoplasm of the mesothelium which is often associated with exposure to asbestos. "For instance, CAR-T cells engineered to co-express CXCR2/CCR2b (receptors for CXCL1) have shown enhanced targeting towards mesothelioma tumor cells expressing CXCL1." (PMID 39539554, 2024).
metastasis (2 papers, 2017 to 2020). The spread or migration of cancer cells from one part of the body (where they first appeared) to another. "CXCL1 expression in cancer cells was significantly correlated significantly with T invasion (T2–T4), lymph node metastasis, lymphatic invasion, venous invasion, peritoneal cytology, peritoneal metastasis, and CXCR2 expression in stromal cells." (PMID 28575019, 2017).
metastatic colorectal cancer (2 papers, 2015 to 2022). "CXCL1 inhibition suppresses CRC tumor growth and warrants further investigation as a candidate therapeutic target in metastatic colorectal cancer." (PMID 26104296, 2015). "CXCL1, is known to promote recruitment and activation of neutrophils, premetastatic niche formation, tumour invasive potential and tumorigenicity in metastatic colorectal cancer patients, and therefore, not surprisingly, serves as a biomarker for poor prognosis." (PMID 35226704, 2022).
neuromyelitis optica (2 papers, 2022 to 2023). A rare inflammatory disease of the central nervous system characterized mainly by attacks of uni- or bilateral optic neuritis (ON) and acute myelitis. "Therefore, CXCL1 levels are elevated in neuromyelitis optica in cerebrospinal fluid and in serum." (PMID 35457023, 2022). "It was found that CXCL1 levels are not correlated with patient clinical severity, which shows that CXCL1 can only be a marker for patients with neuromyelitis optica, but does not affect the development and severity of the disease." (PMID 35457023, 2022).
neuropathic pain (2 papers, 2015 to 2025). Chronic pain caused by damage to nerve fibers. "Notably, in neuropathic pain models, neurons release Cxcl1, linked with pain transmission." (PMID 40889678, 2025).
neutropenia (2 papers, 2019 to 2024). A decrease in the number of neutrophils found in the blood. "High levels of CXCL8 and CXCL1 were associated with increased risk of BSI both in univariate and multivariate analyses adjusted for sex, age, neutropenia, and diagnosis." (PMID 37919603, 2024).
non-melanoma skin carcinoma (2 papers, 2024). "Studies in non-melanoma skin cancer (NMSC) have shown that increased LGALS7 mRNA and Gal-7 protein expression are associated with myeloid programs, elevated CXCL1 levels, and c-MET activation." (PMID 39664377, 2024). "CXCL1 may participate in the formation of non-melanoma skin cancer in a process called photo-carcinogenesis." (PMID 38673949, 2024). "CXCL1 is also involved in tumorigenesis in already-formed non-melanoma skin cancer." (PMID 38673949, 2024).
oral candidiasis (2 papers, 2022 to 2023). Infection of the mucosal lining of the mouth with the fungus Candida albicans. "We examined Ep and CT expression levels of the cytokines IL-1β and G-CSF, known to expand and activate neutrophils during OPC, and the chemokines KC/CXCL1 and MIP-2/CXCL2, which recruit neutrophils in response to oral candidiasis in tongue tissue 6–8." (PMID 37886517, 2023). "Inhibition of EGFR in mouse models of oral candidiasis reduces IL-1β and CXCL1, suggesting EGFR may be the initial receptor responsible for CXCL1-mediated neutrophil recruitment." (PMID 36012793, 2022).
oral mucositis (2 papers, 2023 to 2024). Inflammation of the mucous membranes of any of the structures in the mouth. "Elevated levels of the cytokine IL-6 and the chemokine CXCL1, which are also associated with oral mucositis in humans, were found in the murine model after 5-FU treatment and were normalized by H-MW-HA." (PMID 37479691, 2023). "Pertinently, elevated levels of the cytokine IL-6 and the chemokine CXCL1 are also associated with oral mucositis in humans." (PMID 37479691, 2023).
osteomyelitis (2 papers, 2025 to 2026). An acute or chronic inflammation of the bone and its structures due to infection with pyogenic bacteria. "Among these, macrophages demonstrated a significant increase following osteomyelitis, and the infiltration of Mif+Cd63+, Arg1+Sdc4+, and Cxcl1+Ccl4+ macrophages significantly increased." (PMID 41836400, 2026). "We identified that significant infiltration of Arg1+Sdc4+, Cxcl1+Ccl4+, and Mif+Cd63+ macrophages may affect osteomyelitis through the Ccl3-Ccr1 and Cxcl2-Cxcr2 signaling pathways." (PMID 41836400, 2026).
Pain (2 papers, 2015 to 2019). An unpleasant sensory and emotional experience associated with actual or potential tissue damage, or described in terms of such damage. "These various receptor-mediated events are directly dependent on the CXCL1 or CXCL2 concentration, and dysregulation of these processes e.g., in the pathogenesis of neuropathic pain could switch the cell phenotype." (PMID 31616413, 2019).
papilloma (2 papers, 2022 to 2023). A benign epithelial neoplasm that projects above the surrounding epithelial surface and consists of villous or arborescent outgrowths of fibrovascular stroma. "Accordingly, tumors overexpressing Gal-7 (Tg46) showed a considerably higher percentage of Cxcl1+ cells than WT papillomas, and even higher than Lgals7−/− tumors." (PMID 36693903, 2023). "Though further mechanistic analysis should be performed, our observations in mouse papillomas together with in vitro experiments, suggest that excessive c-Met activation could be responsible for increased Cxcl1 expression and the subsequent recruitment of MDSC to TME." (PMID 36693903, 2023).
Pleural effusion (2 papers, 2022 to 2025). The presence of an excessive amount of fluid in the pleural cavity. "Cytokine array analysis and EIA confirmed that fucoidan lowered the expression levels of inflammatory cytokines such as TIMP-1, CXCL1, MCP-1, MIP-2, and IL-1Ra in pleural effusion of irradiated mice." (PMID 40438605, 2025).
pneumococcal meningitis (2 papers, 2016 to 2023). An acute purulent infection of the meninges and subarachnoid space caused by Streptococcus pneumoniae, most prevalent in children and adults over the age of 60. "In a cohort of 435 pneumococcal meningitis patients and 416 controls we found that variation within CXCL1 and CARD8 were the strongest signals associated with pneumococcal meningitis susceptibility." (PMID 27432718, 2016).
polyp (2 papers, 2024 to 2025). A usually exophytic mass attached to the underlying tissue by a broad base or a thin stalk. "To determine the optimal DSS concentration for an ETBF-induced polyp formation model within this framework, we compared the effects of 1% and 2% DSS on polyp development, survival rate, and circulating levels of IL-17A, CXCL1, and nitric oxide." (PMID 40650003, 2025). "However, CXCL1 was significantly higher in stool from cancer patients compared to the polyp group (p < 0.001)." (PMID 39523395, 2024).
Pseudomonas infection (2 papers, 2016 to 2018). Infections with bacteria of the genus pseudomonas. "However, the association between pseudomonas infection and CLAD was dependent on elevated BALF CXCL1 levels at the time of infection." (PMID 31414076, 2018).
pyelonephritis (2 papers, 2019 to 2023). An inflammatory process affecting the kidney. "Flagellin also activates renal collecting duct cells via TLR5, which enables upregulation of CXCL1 and CXCL2 to provide renal host defense against pyelonephritis." (PMID 31776239, 2019).
rectal adenocarcinoma (2 papers, 2021 to 2023). "In rectum adenocarcinoma, CXCL1 and CXCL3 negatively correlated with EMT, while CXCL5, CXCL6, PPBP, and CXCL8 were positively correlated." (PMID 37686093, 2023). "In rectal adenocarcinoma, four hub genes including CXCL1, CXCL2, CXCL3, and GNG4 were highly expressed at the gene and RNA levels." (PMID 34269159, 2021). "Data from TCGA and GEO verified that overexpression of gene CXCL1 and CXCL3 portends unfavorable survival outcomes in patients with rectal adenocarcinoma." (PMID 34269159, 2021). "In conclusion, the CXCL1 and CXCL3 genes may have potential for prognosis and molecular targeted therapy of rectal adenocarcinoma." (PMID 34269159, 2021).
respiratory failure (2 papers, 2020 to 2021). The significant impairment of gas exchange within the lungs resulting in hypoxia, hypercarbia, or both, to the extent that organ tissue perfusion is severely compromised. "Patients requiring respiratory failure showed depressed CD27, CXCL1, CXCL13, Gal-1, Gal-9, HO-1, IL-18, LAMP3, MCP-3, TNFRS12A." (PMID 34608231, 2021). "Besides expression of pro-inflammatory cytokines, such as IL-1β and TNF-α, the expression of chemokines CCL2, CCL3, CCL20, CXCL1, CXCL3, CXCL10, IL-8 was shown likely to contribute to clinical observation of excessive inflammatory tissue damage, lung injury, and respiratory failure." (PMID 33362782, 2020).
respiratory infection (2 papers, 2017 to 2023). "Next, we wanted to understand how the microbiota drives this common innate response to respiratory infection and whether the effect of the microbiota on enhancing respiratory defenses was mediated by GM-CSF, CXCL1, or CXCL2." (PMID 29142211, 2017).
salivary gland tumors (2 papers, 2022 to 2025). "In patients with salivary gland tumors (WT and PA), various chemokines have been determined, including CCL28, CXCL10, CXCL12, CCL18, and CXCL1, as well as pro-inflammatory cytokines such as IL-1β, IL-6, IL-4, IL-17, and IL-33." (PMID 40807046, 2025). "The levels of IL-1β, CXCL1, and CXCR2 in salivary gland tumors were investigated in this study." (PMID 35626430, 2022).
sarcoma (2 papers, 2023 to 2024). A usually aggressive malignant neoplasm of the soft tissue or bone. "Children with sarcomas have increased blood CXCL1 levels compared to healthy individuals, although a much greater increase occurs in CXCL8/IL-8, whose high blood levels are associated with a poorer prognosis for patients with sarcomas." (PMID 38673949, 2024). "Interestingly, repetitive pre-administration of RvD2 (i.t., 500 ng) suppressed the overexpression of IL-17, CXCL1 as well as GFAP proteins in the dorsal horn following sarcoma exposure (p < 0.05, n = 4)." (PMID 36672133, 2023). "Moreover, the ELISA assay found that anti-IL-17 therapy downregulated spinal CXCL1 expression in the animals undergoing peripheral nerve trauma and sarcoma implantation (p < 0.05, n = 4)." (PMID 36672133, 2023). "As noted, we observed an obvious elevation in the spinal expressions of IL-17, CXCL1 and GFAP in the animals 7 days after sarcoma cell implantation using an ELISA assay (p < 0.05, n = 4)." (PMID 36672133, 2023). "Here, we first reported the spinal rise in IL-17 secretion, CXCL1 release and GFAP expression in mice with peripheral nerve trauma and sarcoma implantation, consistent with nociceptive behaviors of long-lasting mechanical allodynia as well as heat hyperalgesia." (PMID 36672133, 2023).
Splenomegaly (2 papers, 2022). Abnormal increased size of the spleen. "In these animals, splenomegaly was accompanied by higher bacterial burden and higher levels of the pro-inflammatory cytokines IL-6, CXCL1, and MCP-1." (PMID 35248004, 2022).
staphylococcus aureus pneumonia (2 papers, 2014 to 2015). An pneumonia caused by infection with Staphylococcus aureus. "In the respiratory tract, Clca1-/- mice develop decreased levels of Cxcl-1, a potent neutrophil chemoattractant, and of Il-17, a proinflammatory cytokine at the mRNA and protein levels with a consequent decrease in neutrophil response during Staphylococcus aureus pneumonia." (PMID 26162072, 2015).
stomach adenocarcinoma (2 papers, 2023). "To understand the expression pattern of CXCL1 in gastric carcinogenesis, we performed a detailed analysis on TCGA stomach adenocarcinoma (STAD) samples." (PMID 36614235, 2023). "This correlation has been observed in stomach adenocarcinoma with respect to CXCL1, CXCL3, CXCL6, and CXCL8." (PMID 37686093, 2023). "Next, we performed a detailed analysis of CXCL1 promoter methylation levels in TCGA stomach adenocarcinoma (STAD) samples." (PMID 36614235, 2023).
synovitis (2 papers, 2017 to 2022). Inflammation of a synovial membrane. "Recruitment of neutrophils by secretion of macrophage and Th17 lymphocytes (and likely others) by the production of CXCL1 results in synovitis in humans and Lyme arthritis in susceptible C3H strains of mice." (PMID 35924250, 2022). "Recruitment of neutrophils by secretion of macrophage and Th17 lymphocytes (and likely others) by the production of chemokine ligand 1 (CXCL1) results in synovitis in humans and Lyme arthritis in susceptible C3H strains of mice." (PMID 35924250, 2022).